MEFV (MEFV innate immunity regulator, pyrin)
Description:
Involved in the regulation of innate immunity and the inflammatory response in response to IFNG/IFN-gamma. Organizes autophagic machinery by serving as a platform for the assembly of ULK1, Beclin 1/BECN1, ATG16L1, and ATG8 family members and recognizes specific autophagy targets, thus coordinating target recognition with assembly of the autophagic apparatus and initiation of autophagy. Acts as an autophagy receptor for the degradation of several inflammasome components, including CASP1, NLRP1 and NLRP3, hence preventing excessive IL1B- and IL18-mediated inflammation. However, it can also have a positive effect in the inflammatory pathway, acting as an innate immune sensor that triggers PYCARD/ASC specks formation, caspase-1 activation, and IL1B and IL18 production. Together with AIM2, also acts as a mediator of pyroptosis, necroptosis and apoptosis (PANoptosis), an integral part of host defense against pathogens, in response to bacterial infection (By similarity). It is required for PSTPIP1-induced PYCARD/ASC oligomerization and inflammasome formation. Recruits PSTPIP1 to inflammasomes, and is required for PSTPIP1 oligomerization.
Synonyms: MEF; TRIM20; FMF; PAAND
Tractability: Small molecule: a structure with a bound ligand is known. Antibody: its Gene Ontology location is reachable by antibodies, with high confidence; the Human Protein Atlas places it where antibodies can reach. PROTAC: its protein half-life has been measured.
Gene: Protein-coding gene on chromosome 16 (3,240,392 to 3,256,954, reverse strand). Ensembl gene ENSG00000103313.
Subcellular location: Cytoplasm, cytoskeleton (Isoform 1); Cell projection, ruffle; Cell projection, lamellipodium; Nucleus; Cytoplasm; Cytoplasmic vesicle, autophagosome; Nucleus (Isoform 2)
Subcellular location (Human Protein Atlas): Plasma membrane
Pathways (Reactome):
Disease: Purinergic signaling in leishmaniasis infection
Immune System: The NLRP3 inflammasome
Gene Ontology:
Molecular function: actin binding; identical protein binding; protein binding; ubiquitin protein ligase activity; zinc ion binding
Biological process: inflammatory response; negative regulation of cytokine production involved in inflammatory response; negative regulation of inflammatory response; negative regulation of interleukin-1 beta production; negative regulation of interleukin-12 production; negative regulation of macrophage inflammatory protein 1 alpha production; negative regulation of NLRP3 inflammasome complex assembly; positive regulation of autophagy; positive regulation of interleukin-1 beta production; pyroptosome complex assembly; regulation of interleukin-1 beta production; response to type II interferon; innate immune response; pattern recognition receptor signaling pathway; pyroptotic inflammatory response; regulation of gene expression; regulation of inflammatory response; response to other organism
Cellular component: canonical inflammasome complex; cytoplasm; microtubule associated complex; nucleus; plasma membrane; cytosol; microtubule; autophagosome; cytoskeleton; lamellipodium; ruffle
Genetic constraint (gnomAD): Loss-of-function variants: 60 observed, 64.85 expected, observed/expected ratio (o/e) 0.93, 90% interval 0.75 to 1.15. The upper end of that interval is the gene's LOEUF score, 1.15, which puts it in group 5 of 6, group 1 being the genes least tolerant of losing a copy. Missense variants: 1,169 observed, 1,027.4 expected, observed/expected ratio (o/e) 1.14, 90% interval 1.08 to 1.19. Synonymous variants: 500 observed, 425.16 expected, observed/expected ratio (o/e) 1.18, 90% interval 1.09 to 1.27.
Gene-disease validity (ClinGen):
ClinGen rates the evidence that MEFV causes each of these diseases.
familial Mediterranean fever (semidominant): Definitive. Familial Mediterranean fever (FMF) is an autoinflammatory disorder characterized by recurrent short episodes of fever and serositis resulting in pain in the abdomen, chest, joints and muscles.
Homologues: Orthologues: chimpanzee MEFV (98% identical), chimpanzee MEFV (97% identical), macaque MEFV (90% identical), rabbit MEFV (66% identical), dog MEFV (62% identical), mouse Mefv (42% identical), rat Mefv (40% identical). Paralogues in human: TRIM39 (18% identical), TRIM27 (17% identical), TRIM21 (16% identical), TRIM68 (16% identical), TRIM26 (16% identical), TRIM11 (16% identical), TRIM58 (16% identical), TRIM6 (15% identical), TRIML1 (15% identical), TRIM38 (15% identical), MID1 (15% identical), TRIM4 (14% identical), and 68 more.
Diseases named in the same sentence as MEFV in open-access papers:
MEFV is named in the same sentence as 168 diseases in open-access papers, as found by Europe PMC text mining. Sharing a sentence is not in itself a finding about the gene and the disease. The quoted sentences say what the papers report.
familial Mediterranean fever (258 papers, 2008 to 2026). "Familial Mediterranean fever (FMF) is the most common inherited autoinflammatory disorder caused by MEFV variants." (PMID 41801261, 2026). "Familial Mediterranean fever (FMF) is a monogenic autoinflammatory disorder caused by MEFV mutations." (PMID 41393627, 2025). "Mutations in MEFV cause familial Mediterranean fever (FMF), a common hereditary autoinflammatory syndrome." (PMID 40649913, 2025). "The Mediterranean fever (MEFV) gene, primarily linked to familial Mediterranean fever (FMF), has been suggested to have a protective role against SLE." (PMID 40692783, 2025). "These variants included a KCNQ1 variant (c.914G > T, p.Trp305Leu) associated with Long QT syndrome 1 (proband 87), and an MEFV variant (c.2082G > A, p.Met694Ile) associated with Familial Mediterranean fever, autosomal dominant (proband 113)." (PMID 40388540, 2025). "Familial Mediterranean Fever, caused by mutations in the MEFV gene, can present with recurrent sterile serositis such as peritonitis, pleuritis, or pericarditis." (PMID 41523473, 2025). "Familial Mediterranean Fever (FMF) is caused by mutations in the MEFV gene, which encodes for pyrin." (PMID 40493122, 2025). "Familial Mediterranean Fever, a genetic disorder caused by specific mutations of the MEFV gene leading to the dysregulation of the innate immune system, is the monogenic disease more frequently associated to SpA, which is reported in up to 13% of cases." (PMID 40027889, 2025). "Genetic analysis identified a heterozygous M694I mutation in exon 10 of the MEFV gene, which is known to be responsible for familial Mediterranean fever (FMF)." (PMID 41220502, 2025). "MEFV variants are well‐known as a disease‐related factor for familial Mediterranean fever, a representative autoinflammatory disease/syndrome." (PMID 39698752, 2025). "The fact that a variant of MEFV, a gene associated with familial Mediterranean fever, which is a typical autoinflammatory disease, is a predisposing factor for GPP is further evidence that GPP is an AiKD." (PMID 39698752, 2025). "Among these, MEFV gene variants are closely associated with familial Mediterranean fever (FMF), which is aa classic monogenic autoinflammatory disease." (PMID 40861239, 2025). "Other genetic findings included two pathogenic variants associated with atopic dermatitis (FLG, C0120), a VUS for familial Mediterranean fever (MEFV, C037) and one somatic pathogenic variant for myeloproliferative disorder (JAK2, C123)." (PMID 40455168, 2025). "Familial Mediterranean fever is caused by mutations of MEFV that increase the release of the inflammatory cytokines IL-1 and IL-18, resulting in systemic inflammation, and vasculitis in particular." (PMID 39403923, 2024). "Mutations in the MEFV gene cause autoinflammatory diseases, such as Familial Mediterranean Fever (FMF)." (PMID 39201704, 2024). "Pathogenic and likely pathogenic heterozygous variants in the MEFV gene, which encodes an innate immune sensor, lead to the production of inflammatory mediators during infection, and are an established cause of autosomal dominant familial Mediterranean fever." (PMID 39062917, 2024). "Familial Mediterranean fever (FMF) is an autosomal recessive disease caused by mutations in the MEFV gene and is characterized by recurrent febrile episodes of abdominal pain, chest pain, and joint involvement." (PMID 39588206, 2024). "Familial Mediterranean fever (FMF) is a genetic autoinflammatory disease characterized by mutations within the MEFV (MEditerranean FeVer) gene that encodes the pyrin protein." (PMID 39678383, 2024). "Mutations of the MEFV gene cause familial Mediterranean fever characterized by recurrent episodes of fever, peritonitis, and arthritis." (PMID 38177227, 2024). "Mutations within the MEFV gene are accountable for causing the recessive autoinflammatory disease known as familial Mediterranean fever (FMF)." (PMID 38003572, 2023).
familial Mediterranean fever (continued). "The aHUS patient carries a heterozygous E148Q variant in the MEFV gene, which has been associated with the autoinflammatory Familial Mediterranean Fever and was recently molecularly demonstrated to be gain-of-function regarding inflammasome activation." (PMID 37477760, 2023). "Familial Mediterranean Fever is an autosomal recessive inherited disease caused by a mutation in the MEFV (Mediterranean FeVer) gene." (PMID 37759952, 2023). "We found: 1 H-P carries the likely pathogenic variant c.887-2 A>C in the IRF7 gene and 5 H-P carries variants in the MEFV gene, whose role in the pathogenicity of the familial Mediterranean fever (FMF) disease is controversial." (PMID 37760989, 2023). "Variants in MEFV, the gene causing familial Mediterranean fever, was found in 5 patients (two heterozygous E148Q, one heterozygous R202Q, one heterozygous V726A and one compound heterozygous M680I + R202Q)." (PMID 36109811, 2022). "Gain-of-function mutations in the MEFV gene encoding Pyrin cause autoinflammatory disorders, such as familial Mediterranean fever (FMF) and Pyrin-associated autoinflammation with neutrophilic dermatosis (PAAND)." (PMID 36342970, 2022). "In 1997, Mediterranean Fever (MEFV) was the first gene discovered for causing familial Mediterranean fever, the most common hereditary cause of periodic fever." (PMID 36035053, 2022). "In 1997, gain-of-function mutations in MEFV were reported to cause familial Mediterranean fever (FMF)." (PMID 36045928, 2022). "This includes the MEFV gene, which causes the prototypical autoinflammatory disease Familial Mediterranean Fever (FMF)." (PMID 35281022, 2022). "MEFV mutations are responsible for familial Mediterranean fever, that in turn associates with elevated IFN-γ responses." (PMID 36263058, 2022). "As an incidental finding, the proband displayed a common pathogenic variant in MEFV, that has been associated with familial Mediterranean fever and Behcet's disease." (PMID 34148116, 2022). "One example is pyrin inflammasome, and dysregulated pyrin, which is encoded by MEFV, leads to familial Mediterranean fever." (PMID 33766139, 2021). "More than 30 new genes associated with autoinflammatory diseases have been identified since the mutation of Mediterranean fever (MEFV) gene was first discovered as the cause of familial Mediterranean fever (FMF)." (PMID 34884842, 2021). "Familial Mediterranean fever (FMF) is a genetically recessive autoinflammatory disease caused by mutations in the Mediterranean fever (MEFV) gene." (PMID 33315354, 2021). "For example, Familial Mediterranean fever (FMF) is an autosomal recessive self-inflammatory disorder caused by a mutation in the gene encoding MEFV." (PMID 34262554, 2021). "The MEFV gene, best known for causing familial Mediterranean fever (FMF) equally demonstrates the importance of genetics in RDs." (PMID 34294115, 2021). "Mediterranean Fever (MEFV) gene mutations are associated with Familial Mediterranean Fever (FMF) disease, which is an autosomal recessive disorder characterized by fever, serosal inflammation, and recurrent episodes." (PMID 34819953, 2021). "In 1997, MEFV was the first gene identified as disease causing for Familial Mediterranean Fever, the most common hereditary SAID." (PMID 32019685, 2020). "Mutations in the gene MEFV that encodes the protein pyrin leads to familial Mediterranean fever, the prototypic periodic fever syndrome." (PMID 31850638, 2020). "Familial Mediterranean Fever (FMF) is an autosomal recessive auto-inflammatory disease caused by pathogenic variations in the MEFV (for MEditerranean FeVer) gene, located on the short arm of chromosome 16 (16p13.3)." (PMID 32824452, 2020). "Familial Mediterranean fever (FMF) is caused by mutations within the Mediterranean fever (MEFV) gene." (PMID 32655537, 2020). "Pyrin is encoded by MEFV, the gene that is mutated in patients with familial Mediterranean fever (FMF)." (PMID 31456795, 2019).
familial Mediterranean fever (continued). "Familial Mediterranean fever (FMF) is the most common hereditary monogenic autoinflammatory disease caused by mutations in the MEFV gene." (PMID 30714637, 2019). "The diagnosis of Familial Mediterranean Fever was confirmed by the genetic study of MEFV gene; the homozygous mutation M694 V in exon was documented." (PMID 31533789, 2019). "Hyper-activation of the pyrin inflammasome by MEFV-activating mutations causes Familial Mediterranean fever (FMF), a disease that is characterized by high levels of IL-1β, IL-6, IL-8, and IL-12, recurring fever episodes, arthritis, and low bone mass." (PMID 31520179, 2019). "The genetic study for Familial Mediterranean Fever, tumor necrosis factor receptor-associated periodic syndrome, Mevalonate kinase deficiency, showed the homozygous mutation p.M680I of exon 10 in MEFV." (PMID 31443670, 2019). "Familial Mediterranean Fever is a monogenic autoinflammatory disease, secondary to mutation of MEFV gene, and typically expressed with recurrent attacks of fever, serositis, rash, aphthous changes in lips and/or oral mucosa." (PMID 31627741, 2019). "The MEFV gene mutation responsible for familial Mediterranean fever is probably a susceptibility factor for Behçet’s disease, particularly for patients with vascular involvement, and both disorders can occur concurrently in a patient, as in the present case." (PMID 29490685, 2018). "Familial Mediterranean fever (FMF) is an autosomal recessive autoinflammatory disorder caused by mutations in the Mediterranean Fever (MEFV) gene." (PMID 32185329, 2018). "The concept of autoinflammation has evolved over the past 20 years, beginning with the discovery that mutations in the Mediterranean Fever (MEFV) gene were causative of Familial Mediterranean Fever." (PMID 28382039, 2017). "Pretransplant investigations revealed ELANE mutation positive severe CyN along with familial Mediterranean fever (MEFV) mutation." (PMID 28197346, 2017). "Previously, we found preliminary evidence suggesting that familial Mediterranean fever (FMF)-related MEFV variants can affect the disease phenotype of AOSD." (PMID 28899403, 2017). "Familial Mediterranean fever is the most common inherited monogenic autoinflammatory disease worldwide and is caused by loss-of-function mutations in MEFV gene, mostly affecting eastern Mediterranean population." (PMID 28191008, 2017). "The MEFV gene mutations are considered the primary cause of familial Mediterranean fever (FMF), the most common periodic fever syndrome and the prototype of monogenic autoinflammatory disease (AID)." (PMID 27364639, 2016). "The prototype is Familial Mediterranean Fever, a monogenic hereditary disorder, whose causing gene (MeFV gene) was identified in 1997 and opened the way to a new fascinanting chapter of rheumatology." (PMID 25969671, 2015). "The prototype is Familial Mediterranean Fever, a monogenic hereditary disorder, whose gene causing (MeFV gene) was identified in 1997 and opened the way to a new fascinanting chapter of rheumatology." (PMID 25969671, 2015). "Familial Mediterranean fever (FMF) is a genetic autoinflammatory disorder caused by mutations in the chromosome 16 MEFV gene, encoding the protein pyrin." (PMID 25147819, 2014). "Missense mutations in the MEFV gene responsible for familial Mediterranean fever can differ quite dramatically in terms of their clinical penetrance." (PMID 23820649, 2013). "Familial Mediterranean fever (FMF) is an autosomal recessive autoinflammatory disorder due to MEFV mutations and one of the most frequent Mediterranean genetic diseases." (PMID 23844200, 2013). "Familial Mediterranean fever (FMF) is an auto inflammatory disorder caused by mutations within the MEFV (Mediterranean Fever) gene, which lead to ongoing activation of pro inflammatory pathways." (PMID 22811950, 2012).